RPL30P1 (ribosomal protein L30 pseudogene 1)
Synonyms: RPL30_1_127
Gene: Processed pseudogene on chromosome 1 (174,090,136 to 174,090,474, reverse strand). Ensembl gene ENSG00000225713.
Diseases named in the same sentence as RPL30P1 in open-access papers:
RPL30P1 is named in the same sentence as 2 diseases in open-access papers, as found by Europe PMC text mining. Sharing a sentence is not in itself a finding about the gene and the disease. The quoted sentences say what the papers report.
Headache (1 paper, 2022). Cephalgia, or pain sensed in various parts of the head, not confined to the area of distribution of any nerve. "Of the genes at these loci, six (FAF1, TMX2-CTNND1, AARSD1, PLCD3, ZNF652, and C20orf203; headache-TSH) and six (HMGB1P45, RPL30P1, ZNF462, TMX2-CTNND1, ITPK1, SECISBP2L; headache-fT4) were significant in our gene-based analysis (pFisher’s combined p-value < 2.09 × 10−6)." (PMID 36672757, 2022).
migraine (1 paper, 2022). "Interestingly, some of these loci mapped to genes including ITPK1, ZNF462, RPL30P1, ANKDD1B, THADA, ZNF652, and C20orf203 that have been reported as genome-wide significant in the most recent migraine GWAS." (PMID 36672757, 2022).